RN7SKP233 (RN7SK pseudogene 233)
Gene: Miscellaneous RNA gene on chromosome 16 (76,287,630 to 76,287,739, forward strand). Ensembl gene ENSG00000252814.
Homologues: Orthologues: chimpanzee 7SK (99% identical), mouse Gm55584 (53% identical), guinea pig 7SK (39% identical). Paralogues in human: RN7SKP65 (82% identical), RN7SKP115 (80% identical), RN7SKP175 (80% identical), RN7SKP20 (80% identical), RN7SKP139 (79% identical), RN7SKP224 (79% identical), RN7SKP25 (79% identical), RN7SKP255 (79% identical), 7SK (78% identical), RN7SKP113 (78% identical), RN7SKP118 (78% identical), RN7SKP162 (78% identical), and 284 more.